EPCAM (epithelial cell adhesion molecule)
Diseases named in the same sentence as EPCAM in open-access papers (continued):
Sharing a sentence is not in itself a finding about the gene and the disease.
tumor (continued). "It detects combinatorial abnormalities in protein biomarkers (e.g., CK, EpCAM, VIM, HER2, and PD‐L1) and chromosomal aneuploidy (e.g., chromosome 8 polysomy) tailored to tumor profiles." (PMID 40437761, 2025). "In line with TAA expression on PDAC cell lines, EpCAM, TROP2 and MUC1 were the most abundant expressed TAA on patient tumor cells." (PMID 40358156, 2025). "H-scores of CEA, EpCAM, c-MET, and EGFR were compared between tumor and adjacent normal epithelial tissues using pre- and post-treatment specimens." (PMID 40563608, 2025). "Heterogeneity of the tumor or changes in cellular phenotype, as epithelial‐to‐mesenchymal transition (EMT), can diminish EpCAM expression or impede its detection." (PMID 40525275, 2025). "This approach surpasses reliance on imaging modalities, such as EpCAM and CEA, novel targets used in tumor-target imaging approaches." (PMID 39399490, 2024). "Genetic parsing of a variety of tumor stem cells has revealed that tumor stem cells contain specific markers, such as CD24, CD44, CD133 and EpCAM, whose importance for the maintenance and activity of tumor stem cells is unclear." (PMID 39744013, 2024). "Both tumor hypoxia and the number of TSD+ EpCAM+/ABCG2+ CSCs were increased significantly in the cisplatin++ group between the 2nd and 8th weeks of tumor growth." (PMID 39963656, 2024). "EPCAM, also known as CD326, is expressed in normal human epithelial cells and most epithelial tumor cells." (PMID 40836974, 2024). "We observed a notable shift in immune cell infiltration upon loss of tumor cell‐intrinsic Sin3B, with a marked increase in total immune cells (CD45.2+) and a decrease in tumor cells (CD45.2−; EpCAM+)." (PMID 39316363, 2024). "Distinct cell clusters of EGFR-high and CCNE1-high cells were found predominantly in the EpCAM+ clusters in TNBC, where EGFR was expressed in 23.1% ± 1.6% of EpCAM+ cells, compared with 4.4% ± 0.7% in HER2+ and 3.5% ± 0.5% in ER+ tumor cells." (PMID 38772416, 2024). "When we transplanted these relapsed tumors into NSG mice and administered fresh EpCAM CAR T cell products, we observed a modest partial response to CAR T cell therapy, despite a substantial expansion of CAR T cells within the tumor." (PMID 38550578, 2024). "Both EpCAM and TROP2 immunostaining data were available for 10,998 tumors from 101 tumor categories." (PMID 38786342, 2024). "Catumaxomab, a trifunctional bispecific antibody targeting EpCAM-expressing tumor cells, CD3-expressing T cells, and antigen-presenting cells, was approved for treating malignant ascites of patients with positive EpCAM." (PMID 38609981, 2024). "However, the fundamental limitation is that a subpopulation of metastatic tumor cells undergoing epithelial-to-mesenchymal transition will lose EpCAM expression, while some leukocytes may be activated for EpCAM, causing inaccurate detection using this approach." (PMID 39050821, 2024). "In the experimental group treated with EpCAM-CAR-T cells, the survival rate of nude mice was higher (P < 0.05), and the tumour was smaller than that in the blank and control groups (P < 0.05)." (PMID 39107717, 2024). "Circulating tumor cells (CTCs) are detected in approximately 30% of metastatic non-small-cell lung cancer (NSCLC) cases using the CellSearch system, which relies on EpCAM immunomagnetic enrichment and Cytokeratin detection." (PMID 39337304, 2024). "In another study, HUH-7 treatment with doxorubicin resulted in a significant increase in EpCAM/CD133 expression along with augmented stemness and tumor formation ability." (PMID 38773585, 2024). "The S-UMAP analysis revealed highly significant correlations between EpCAM in lymphoid restricted regions, where elevated IFNγ and NOS2 were expressed, either at the tumor edge or in tumor satellites areas." (PMID 39356141, 2024).
tumor (continued). "To overcome its off-target cytotoxicity and insolubility and for tumor-specific localization, we encapsulated 2c in PLGA (US-FDA-approved polymer) nanoparticles conjugated with aptamer (Apt-2cNP) that bind EpCAM." (PMID 39164686, 2024). "Epithelial cell adhesion molecules (EpCAM, CD326) are expressed on CSCS of multiple tumor types, including colon and liver cancer." (PMID 38355636, 2024). "Salvia in this study showed apparent anti-CSCs activity by reducing expressions of EpCam and ALHDH1 proteins in tumor cells in vivo." (PMID 38464730, 2024). "In parallel, stainings for EpCAM and the pan immune cell marker CD45 were used to identify tumor cells and to assess immune cell infiltration, respectively." (PMID 39246414, 2024). "EpCAM-targeted CAR-T cells suppressed peritoneal metastases in mouse models, while CEA-specific CAR-T cells showed improved tumor infiltration and efficacy when combined with cytokines like IL-12 or when delivered intraperitoneally." (PMID 39684219, 2024). "Intratumoral numbers of EpCAM/GFPCAR T-cell exceed those of GFPT-cell illustrating target tropism and successful tumor infiltration." (PMID 39358663, 2024). "Our findings demonstrate the efficacy of EpCAM-directed CAR T-cell after intracerebral administration, resulting in a reduced tumor growth and prolonged survival." (PMID 39358663, 2024). "In this study, we used CD45, EpCAM, and CK7/8 to identify circulating tumor cells (CTCs, CD45-EpCAM+ CK7/8+), as well as circulating cancer cells exhibiting monoexpression of epithelial markers—CD45-EpCAM+CK7/8 and CD45-EpCAM-CK7/8+ (Epit-CCs)." (PMID 38806508, 2024). "This detection method can identify non‐epithelial tumor cells and those that have undergone EMT and lost detectable EpCAM expression, making it applicable to a wide range of cancer types." (PMID 39302034, 2024). "The expression of the epithelial transcript marker EPCAM coincided with the expression of COL18A1, TNC and COL12A1 gene transcripts in the tumor clusters." (PMID 39239354, 2024). "The only CSC marker that was consistently reliable across all tumor entities was CD90, and thus, the remaining tumors (up to 145) were analyzed for AF and CD90, as well as EpCAM." (PMID 39225547, 2024). "Regarding the expression of transcription factor genes, the expression was higher in EPCAM-positive CTCs (CDH1, ZEB1, ZEB2) and in EPCAM-positive primary tumor cells (CDH1, SNAIL1, SNAIL2, ZEB2) compared to EPCAM-negative CTCs and tumor cells." (PMID 39456890, 2024). "Flow cytometry analysis of the TME revealed both PD-L1 and MHC-I expression on CD45+ leukocytes, CD45.2−/EpCAM+ tumor cells and CD45.2−/EpCAM−/CD90.1+ CAFs." (PMID 39009951, 2024). "We firstly analyzed the correlation between the expression of TRIM71 and tumor stem cell markers in HCC and HB and found significant positive correlation between TRIM71 and CD133, CD24, EPCAM, and LGR5 in HCC and HB tumor samples." (PMID 39267787, 2024). "The percentage of tumor cells expressing AF, CD90, EpCAM, and EpCAM/AF was determined by flow cytometric analysis." (PMID 39225547, 2024). "Surface biomarkers such as CD44, CD90, epithelial cell adhesion molecule (EpCAM) and CD133 are utilised to identify tumour stem cells in HCC, whose activation profoundly drives the malignant progression of the disease." (PMID 39462685, 2024). "In this mechanism, a subset of EpCAM+/ABCG2+ cells (TSD+ CSCs) behave altruistically to protect the dormant R-CSCs, ultimately enhancing the overall fitness of the tumor." (PMID 39963656, 2024). "Multiplex immunofluorescence staining assays further revealed that IL-4 was well colocalization with cancer cell marker EpCAM and POSTN was mainly distributed in tumor stroma." (PMID 38773979, 2024). "The epithelial cell marker genes EPCAM, KRT19, and KRT7 were used to annotate tumor cells that were further verified copy number variations." (PMID 39474422, 2024).
tumor (continued). "In 4T1 tumor tissue lysate, we also analyzed the expressions of OPN and EpCAM, and we found that calcitriol, in mice fed VD3 normal (1000 IU + cal) and deficient (100 IU + cal) diets, significantly increased OPN levels." (PMID 38355711, 2024). "T cells transfected with EpCAM-CAR demonstrated the ability to effectively target and recognise EpCAM-positive tumour cells." (PMID 39107717, 2024). "Significant upregulation in the gene expression level of tumor stem cell markers CD24, CD44, CD133, and EPCAM were also observed in the 3D Mixed organoids compared to both HUH-7 cell line and 3D HUH-7 organoids." (PMID 38773585, 2024). "However, the anti-tumor effects of combining anti-EpCAM antibodies with IL-2v remain unclear." (PMID 39595576, 2024). "The combination therapy consisting of EpCAM-specific CAR-NK cells and regorafenib showed stronger antitumor activity than monotherapy against CRC cells and tumor-bearing mice." (PMID 38254219, 2024). "In another study, the combination of bispecific EpCAM × CD3 antibody and umbilical cord blood mononuclear cells (MNCs) derived from mouse liver inhibited tumor growth in SW480 tumor-bearing mice." (PMID 38254219, 2024). "The high expression of tumor-related genes (EPCAM, CD24, CDH1, ELF3, KRT18, KRT19, KRT8, and MUC1) in groups 10 and 11 suggests that cells in these groups are tumor cells." (PMID 38693422, 2024). "Pairwise comparison revealed significant differences (q ≤ 0.05) in the expression of all markers between PBMCs and tumor cells, with the exception of SLFN11 and AR-V7 between PBMCs and PC-3 cells, and EPCAM, PSA, and PSMA between PBMCs and NCI-H1299 cells." (PMID 39550585, 2024). "Tumor-derived EVs were identified by EpCAM and PD-L1 nucleic acid ligands, induci ng the “AND” logic operation, whereas non-tumor-derived PD-L1+ EVs only express PD-L1, thus invoking the “NOT” logic operation." (PMID 38793203, 2024). "Initially, it was used for measuring EpCAM protein expression, a standard marker for CTC detection, revealing higher levels in single MCF-7 over MDA-MB-231 tumor cells." (PMID 39304879, 2024). "EPCAM and KRT8 were abundantly expressed in tumor epithelial tissue with scattered expression of CD14 and CD163 in monocytes/macrophages." (PMID 38611120, 2024). "The bispecific antibody 4224 activates T lymphocytes to attack tumor cells, targeting CD40 and EpCAM in tumor exosomes." (PMID 36978715, 2023). "Solitomab is an EpCAM/CD3 BiTE bispecific antibody demonstrated to stimulate CD4 and CD8 positive T-cells and reactivate tumor-resident T-cells to deplete cancerous cells." (PMID 37895932, 2023). "While we found that adding intercellular adhesion molecule 1 (ICAM-1) targeting can enhance EpCAM CAR T cell activity, resistance and tumor recurrence remained significant challenges." (PMID 38067255, 2023). "The RNAscope for THBS1 transcript and co-immunofluorescence of THBS1 with epithelial marker EPCAM confirmed the localization of THBS1 in the stroma, which was supported by transcriptomic analysis showing higher THBS1 expression in the tumor stroma." (PMID 37749092, 2023). "Analysing this dataset for EpCAM, Vimentin and CD24 co-expression, we found that 12% of tumour cells (267/2215) were EpCAM+Vim+CD24+." (PMID 37975646, 2023). "In summary, we describe the development of CEA and EpCAM specific adaptor RevTMs for monospecific and AND-gated targeting of CRC cells via the RevCAR platform as an improved approach to increase tumor specificity and safety of CAR T-cell therapies." (PMID 38169746, 2023). "Specifically, as tumor cells highly express epithelial features, typical epithelial markers including KRT8 and EPCAM are highly expressed in 6 clusters (0, 3, 6, 9, and 10)." (PMID 37479733, 2023). "A study developed a model, called EVsum5, based on the combination of LMP1, LMP2A, and the tumor markers programmed death 1 (PD-L1), epidermal growth factor receptor (EGFR), and epithelial cell adhesion molecule (EpCAM) to identify five EV subpopulations." (PMID 36968209, 2023).
tumor (continued). "At the endpoint of inoculation days, the tumors generated from SCARB2 knockout tumor spheroids showed the decreased proportions of CD24, EpCAM, CD13, or CD133 positive cells." (PMID 37739936, 2023). "We also verified the positive correlation between ID1 expression and SOX9 (p = 6.90e‐05, r = 0.20), EPCAM (p = 5.37e‐06, r = 0.23), CD24 (p = 1.82e‐07, r = 0.27), and CLDN4 (p = 6.04e‐05, r = 0.18) expression in HCC tumor tissue from TCGA datasets." (PMID 37085918, 2023). "Here, we characterise the combined role of EpCAM and CD24 in marking a population of disseminating tumour cells in human OSCC specimens." (PMID 37975646, 2023). "We focused on the following tumor-related antigens found in BC: HER2, TROP2, EGFR, CD276, and EpCAM." (PMID 38201595, 2023). "Single cells co-expressing EpCAM, Vimentin and CD24 were abundant in the stroma surrounding metastatic tumours." (PMID 37975646, 2023). "EPCAM, PLAU and THBS1 were shown to be induced within TDLNs secondary to the afflux of tEV from primary tumor, and are involved in tumor cell recruitment and extra-cellular matrix remodeling." (PMID 38074683, 2023). "We have shown that immunofluorescent antibody co-staining for EpCAM, Vimentin and CD24 can separate disseminating EMT CSCs from the stromal content of human tumours, a challenge which has confounded previous attempts to develop a predictive EMT signature." (PMID 37975646, 2023). "A recent publication in Nature showed that in pancreatic adenocarcinoma (PDAC), the primary source of Grem1 expression is derived from tumor cells that have undergone epithelial-to-mesenchymal transition (EMT) and lost EpCAM expression." (PMID 37615860, 2023). "Expression of EpCAM, Vimentin and CD24 was then analysed for every nucleated cell in every imaging field that included both tumour and stroma (3500 manually curated imaging fields across the 24 tumours)." (PMID 37975646, 2023). "Aptamers against EpCAM, CD44, and CD133 have been used widely as targeting ligands to guide therapeutic agents to CSCs in different tumor types." (PMID 36969696, 2023). "All tumor cells showed high expression in signature genes of pancreatic epithelial lesion, like KRT19, MUC1, EPCAM and CEACAM6." (PMID 37007745, 2023). "These were trained using the CD24+EpCAM+VIM+-positive cell counts for each field of view, separated into tumour body and stroma using our imaging segmentation pipeline." (PMID 37975646, 2023). "To date, various specific tumor markers, including HER2, PSA, EGFR (epidermal growth factor receptor), EpCAM, and MUC1 (mucin-1) have been used to isolate CTCs; among these, EpCAM has been extensively used." (PMID 37759483, 2023). "The synergistic effects of regorafenib and CAR NK-92 cells, which recognize EpCAM+ CRC cells, and release cytokines, such as IFN-γ, perforin, and granzyme B, while reducing tumor xenografts in mice, were observed." (PMID 37175871, 2023). "Immunohistochemistry (IHC) staining for BTBD16, EpCAM, FOXM1, AGXT and JMJD1C was carried out in normal and tumor thyroid tissue samples (three patient biopsies available), belonging to two NMTC families: NMTC_1 and NMTC_4." (PMID 37175550, 2023). "In line with studies from others, in our mouse model, the CCA tumor component within the cHCC-CCA tumors from the HE and HO mice stained positive for the progenitor markers SOX9 and EpCAM." (PMID 37627221, 2023). "Epithelial cell adhesion molecule (EpCAM, also known as CD326) is a single-channel type I plasma membrane glycoprotein expressed in a variety of tumor epithelial cells that is commonly used as primary tumor cell marker." (PMID 37626402, 2023). "EPCAM+, EPCAM− and EPCAM−Rhoj-KO tumour cells similarly increased the level of phosphorylated ATM/ATR substrates after cisplatin/5FU administration, showing that RHOJ does not control ATM and ATR activation after chemotherapy." (PMID 36949199, 2023). "Tumor sections were stained with CSC biomarkers (CD44, c-Myc, EpCAM) and macrophage biomarkers (F4/80, CD68)." (PMID 37553567, 2023).
tumor (continued). "Within pT2-4 carcinomas, the TROP2 and EpCAM staining level was unrelated to pT, grade, UICC-category, and overall or tumor-specific patient survival." (PMID 38282671, 2023). "By combining EpCAM as a tumour lineage and EMT CSC marker, Vimentin as a mesenchymal marker, and CD24 as a plastic EMT CSC marker, we aimed to identify tumour cells that have undergone EMT and disseminated into the surrounding stromal region." (PMID 37975646, 2023). "In this study, we employed a combination of the tumor molecular markers CK20, Pan-CK, and EpCAM to detect metastatic tumor cells in LNs from (CRC) patients." (PMID 38152574, 2023). "In vivo XPAT protein unmasking was assessed in five PDX tumor models with HER2-XPAT protein and an additional five PDX models with an XPAT prototype targeting human EpCAM (EpCAM-XPAT)." (PMID 36997747, 2023). "Examining disseminating tumour cells in over 12,000 imaging fields from 74 human oral tumours, we see a significant enrichment of EpCAM, CD24 and Vimentin co-stained cells disseminating beyond the tumour body in metastatic specimens." (PMID 37975646, 2023). "Immunohistochemical analysis confirmed the expression of ALDH1A1, CD44, and EpCAM in both TN and NAT tumor tissues." (PMID 36400567, 2023). "The DSP analysis unveiled a decrease in molecules that promote tumour growth, such as CHIL3, EpCAM, MMP7 and several pathways, including CAM and PI3K‐AKT signalling pathway." (PMID 38131168, 2023). "The cellularity dynamics differed significantly after cisplatin treatment of EpCAM+CD44-CD24-/+ subpopulations of BT-474 and T47D tumour cell lines." (PMID 37345102, 2023). "Due to the limitations of the epithelial marker EpCAM, the application of positive selection strategies that target mesenchymal (e.g., vimentin or N-cadherin), stem cell (e.g., CD133), or tumor-specific markers can be beneficial." (PMID 37759483, 2023). "Together, these results indicated that the LeptoM3 and BCB adhesion cells expressed higher stemness markers CD44, CD133, and EPCAM and lower CD24 and the overexpression of ICAM2 promoted sphere formation and tumor initiation." (PMID 37620448, 2023). "The high purity of the fibroblast and tumor cell populations was confirmed by selective expression of cell type-specific genes including CDH1, EPCAM, and KRT8 for tumor cells and VIM, DCN, THY1, and COL3A1 for fibroblasts." (PMID 36868311, 2023). "Preferential unmasking of fluorophore-labeled HER2-XPAT and EpCAM-XPAT proteins was evident in tumors 48 h after administration to BT-474 and PDX tumor-bearing mice versus heart, brain, liver and spleen tissues." (PMID 36997747, 2023). "qPCR analysis showed that the expression of CD133, CD44, and OCT4 and SOX2, EpCAM, and LGR5 in CSC sphere cells enriched after the addition of micro serum was higher than that in tumor cell spheres enriched in serum-free medium." (PMID 37639070, 2023). "Several known stem markers, including the EPCAM, MUC1 and CD44 signatures, promote transformation and tumour progression." (PMID 36661191, 2023). "In our current study, Sel‐GemPac treatment not only inhibited the EpCAM transcript, but also suppressed the protein expression significantly in KPC mice tumour." (PMID 38131168, 2023). "By fusing EpCAM-specific DARPins to the AAV2 capsid, researchers have successfully developed tumor-targeted AAV vectors, such as EpCAM-AAV and PTS-coupled AAV." (PMID 38082377, 2023). "On the other hand, recurrent tumor acquires an expression signature characterized by high CD117 and low EpCam expression as was observed for highly aggressive SK-OV-3 cells." (PMID 36875773, 2023).